CACNA1D (calcium voltage-gated channel subunit alpha1 D)
Diseases named in the same sentence as CACNA1D in open-access papers (continued):
Sharing a sentence is not in itself a finding about the gene and the disease.
renal dysfunction (1 paper, 2021). "The odds of renal dysfunction were higher in variant carriers of PPP3CC rs10108011, PPP3CC rs2461494, and PRKAG2 rs7805747, whereas the odds of renal dysfunction were lower in variant carriers of CACNA1D rs893365 and NR3C2 rs1490453." (PMID 33868389, 2021).
resistant hypertension (1 paper, 2021). "The CACNA1D gene, encoding the alpha-1D subunit of the calcium channel, showed suggestive evidence of an association with resistant hypertension." (PMID 34593835, 2021). "On the other hand, our GWAS discovered a suggestive association with resistant hypertension in the CACNA1D and CYP11B2 regions using a Japanese population, with high prescription rates for calcium channel blockers and angiotensin receptor blockers." (PMID 34593835, 2021).
sarcoma (1 paper, 2021). A usually aggressive malignant neoplasm of the soft tissue or bone. "The same study reported low CACNA1D-expression in sarcoma and renal tumors." (PMID 36046118, 2021).
testis cancer (1 paper, 2015). "CACNA1F only showed high expression in testis cancer, whereas CACNA1A, CACNA1C, and CACNA1D were highly expressed in most types of cancer." (PMID 26147197, 2015).
cancer (35 papers, 2015 to 2025). A tumor composed of atypical neoplastic, often pleomorphic cells that invade other tissues. "Among the CaVs, CaV1.3, encoded by CACNA1D, was recently reported to be upregulated in cancer tissues compared to related normal tissues." (PMID 39958978, 2025). "At the COSMIC Cancer Gene Census gene level, CACNA1D, PIK3CA, and WNK2 mutations belonged to the dMMR-like type of NECC." (PMID 37920164, 2023). "The finding of an association between colorectal cancer and CACNA1D strongly suggests a new direction for cancer diagnosis and treatment." (PMID 26147197, 2015). "Notably, the VGCC subunit CaV1.3 is frequently dysregulated in various cancers, with its encoding gene CACNA1D exhibiting elevated expression across diverse malignancies." (PMID 41155636, 2025). "The expression of CaV1.3 correlates with patient prognosis, and mutations in the CACNA1D gene in cancers are becoming clearer, so that CaV1.3 may also be used as a potential marker for determining risk of disease, prognosis, and so on." (PMID 39365143, 2024). "Finally, we have identified mRNAs encoding proteins such as IL2RG (155%), GNRH1 (153%) and CACNA1D (130%) that are overexpressed and whose role in cancer remains unclear." (PMID 40096084, 2025). "Multiple Ca2+-handling proteins, including CACNA1D, CACNA2D1, TRPV4, TRPV1, TRPM4, MCU, and RyR1, exhibit cancer-associated overexpression or functional changes, correlating with poor prognosis and aggressive disease features." (PMID 41226294, 2025). "Of the 17 cancers in the dataset, CACNA1D expression was greatest in PCa, suggesting contribution to the development, progression, or treatment response of PCa." (PMID 36949059, 2023). "CACNA1D overexpression in PCa has been reported previously and our analysis of large TCGA datasets demonstrated high CACNA1D expression across a range of cancers." (PMID 36949059, 2023). "Box and whisker plots (median, 10th, 90th percentiles) demonstrated CACNA1D transcript abundance in each cancer type, arranged in descending mean FPKM order." (PMID 36949059, 2023). "When we limited the analysis to the genes of the COSMIC Cancer Gene Census Tier 1, only four genes, including ATP2B3, CACNA1D, KRAS, and PIK3CA, showed recurrent mutations only in two patients." (PMID 37920164, 2023). "We also found that 9 of the 21 tissue sections from cancer patients showed overexpression, with CACNA1D categorized in the top 10% of the most elevated genes." (PMID 26147197, 2015). "High expression of CACNA1D correlated with various types of cancer." (PMID 40352930, 2025). "Moreover, knockdown of CACNA1D resulted in a diminished calcium influx, which, in effect, inhibited cancer cell growth, proliferation, and migration." (PMID 41226294, 2025). "So, the Cacna1d, Kcnj12 Tgfb2, Cav1, Mecom, Kitlg, and Bmp2 genes had associations with any of the five pathways of PC1 (glutamatergic synapse, cholinergic synapse, proteoglycans in cancer, pathways in cancer, and MAPK signaling pathway)." (PMID 40076966, 2025). "As the ‘dark matte’ of the genome, non‐coding RNAs have attracted much attention in recent years, and some studies suggest that non‐coding RNA molecules may regulate CACNA1D and its downstream signalling pathways to affect cancers." (PMID 39365143, 2024). "On the other hand, CACNA1D was found to be selectively upregulated in path C, which could presumably provide a mechanism for these more differentiated cancer types to overcome hormonally regulated suppression of growth." (PMID 39347576, 2024). "Such associations with improved survival may be due to the potential effect of CACNA1D on Ca2+-dependent cancer-cell death." (PMID 36046118, 2021).
cancer (continued). "Notably, two trunk genes (SPEN and ITK), a branch gene (SMARCE1), and several private genes (FAT4, CACNA1D, ATR, RUNX1T1, TERT, and SRGAP3) were defined as cancer-associated genes, according to the cancer gene census." (PMID 28716121, 2017). "CACNA1D may simultaneously promote PCa cell growth and proliferation, and thus play a generalized, supporting role in castration-resistant cancer progression." (PMID 27196083, 2016). "The observation of overexpression of CACNA1A, CACNA1C, and CACNA1D could make them likely targets in cancer treatment, as it suggests that blockage or partial inhibition of their expression could help to modulate the status of metastatic diseases." (PMID 26147197, 2015). "In particular, there is some recent evidence suggesting that CACNA1D overexpression may induce prostate carcinogenesis and that these cancer-promoting effects may be counteracted by inhibition of the gene or the protein it encodes." (PMID 26692910, 2015). "Our in silico analysis suggests that CACNA1D may be a novel oncogene in cancer development, but further experiments are needed to explore the details of the role of CACNA1D in cancer progression." (PMID 26147197, 2015). "Therefore, CACNA1D is a potential prognostic marker for some cancers." (PMID 39365143, 2024). "Greatest mean CACNA1D expression occurred in PCa (FPKM:5.93) followed by breast (FPKM: 2.58), pancreatic (FPKM: 1.96) and colorectal (FPKM:1.75) cancers in agreement with previous studies." (PMID 36949059, 2023). "We found that the targets of nifedipine, such as voltage-dependent L-type calcium channel subunit alpha-1C (CACNA1C), subunit alpha-1D (CACNA1D) and beta-2 (CACNB2), have important links to cancer development and progression." (PMID 33893730, 2021). "Finally, we have also showed the overexpression of genes whose role in cancer is not yet well understood such as IL2RG, CACNA1D and GNRH1." (PMID 40096084, 2025). "Although the mechanisms of CACNA1D in regulating cancer metastasis was not completely elucidated, general views illustrate that calcium channels in degradation of the extracellular matrix and the cellular migration, play a pivotal role in this process." (PMID 39365143, 2024). "Hovewer, this phosphosite does not appear to be conserved in the CACNA1D or CACNA1S isoforms identified in our study as drivers of filopodia formation in cancer cells." (PMID 27910855, 2016). "Results of the GO and KEGG analyses revealed that CACNA1D was enriched in the GO entries “neurotransmitter transport” and “cellular localization” and in the KEGG entry “Herpes simplex virus 1 infection”, and may be a novel oncogene in cancer development." (PMID 34566889, 2021). "As for TDRD1 and PLA2G7, progression-associated overexpression of CACNA1D may be largely independent of ERG-status in these cancers, and apparently occurs also in ERG-negative cancers." (PMID 27196083, 2016). "Importantly, individual silencing of CACNA1D or CACNA1S gene expression using multiple siRNA oligos decreased both filopodia formation and cancer cell invasion, indicating that CACNA1D and CACNA1S are likely to synergistically support filopodia formation and cancer cell invasion in MDA-MB-231 cells." (PMID 27910855, 2016).
tumor (25 papers, 2014 to 2025). "One study identified higher expression of the zona glomerulosa-associated gene NPNT in ATPase-/CACNA1D -mutated tumours compared to KCNJ5-mutated tumours." (PMID 31000732, 2019). "The results of qPCR detection of tumor samples revealed that when compared with the control group, the mRNA expression of CACNA1D in the NTD group and OXA group decreased, and the combination group remained the lowest." (PMID 39958978, 2025). "Significant CACNA1D overexpression was found in primary and metastatic PCa tumours, compared to adjacent benign prostate tissue." (PMID 36949059, 2023). "Somatic mutations in KCNJ5, ATP1A1, ATP2B3, CACNA1D and CTNNB1 have been described in ~60% of these tumours." (PMID 31000732, 2019). "However, the mechanism by which PIK3R3, ITGB8, TrkB, and CACNA1D induce cell autophagy and inhibit tumor growth remains to be elucidated." (PMID 36386893, 2022). "Based on the in vitro transcriptome analysis and validation of “cytokine-cytokine receptor interaction,” “PI3K-Akt signaling pathway” and “MAPK signaling pathway,” we measured the relative protein expression of TGFB2, INHBB, PIK3R3, ITGB8, NTRK, and CACNA1D in tumor tissue." (PMID 36386893, 2022). "In the fifteen tumours subjected to RNA-Sequencing in this study, opposite patterns of expression in tumours with mutations in KCNJ5 and those with mutations in CACNA1D/ATP1A1/ATP2B3 were observed, with KCNJ5-mutants showing higher levels of CYP11B1 expression and lower levels of CYP11B2 expression." (PMID 31000732, 2019). "In addition, silencing of PLA2G7, RHOU, ACSM1, LAMB1 and CACNA1D also resulted in reduced tumor cell invasion in PC3 organoid cultures." (PMID 27196083, 2016). "Regarding pathway assignments of at least 20 HRO tumours, 10 top-ranked genes, of which 9 were lost in 3p, were linked with 7 to 45 pathways (n = 280) comprising RAF1 (45 PWs), RHOA (25 PWs), IPTR1 (22 PWs), CACNA1D, ITGA9 (8PWs), WNT7A (8 PWs) TLR9 (7PWS9, LAMB2 (7 PWs) and ARPC4 (6 PWs)." (PMID 28486536, 2017). "CACNA1D, JPH1, and ATP2C2 were also upregulated in advanced OAC tumor grades and nodal-metastatic stages in both datasets." (PMID 36046118, 2021). "Three genes (CACNA1D, CACNA2D1, and CACNA2D2) coding for the α subunit of voltage-dependent Ca2+ channels were down-regulated in tumor tissues." (PMID 24466154, 2014). "In contrast to humans, CACNA1C expression was much greater than CACNA1D in both feline tumor and nontumor adrenal tissue." (PMID 39429164, 2024). "VCGG channels, including CACNA1C, CACNA1D, CACNA1F, CACNA1E, CACNA1A, CACNA1G, CACNA1I, showed significantly higher expression in KIRC than normal cases, whereas CACNA1S and CACNA1H showed higher expression in normal than tumor cases." (PMID 36588677, 2022). "Furthermore, there were significant differences in the transcription levels of CACNA1D, JPH1, and ATP2C2 between various tumor grades and nodal-metastatic stages in both datasets." (PMID 36046118, 2021).
neurodevelopmental disorder (10 papers, 2015 to 2026). A behavioral and cognitive disorder with onset during the developmental period that involves impaired or aberrant development of intellectual, motor, or social functions. "We show that this algorithm reliably predicts known pathogenic variants for CACNA1D-associated neurodevelopmental disorders and treatment-resistant hypertension, and also improves pathogenicity classification of variants of yet unclear significance." (PMID 38553610, 2024). "Recent human genetic studies have linked a variety of genetic variants in the CACNA1C and CACNA1D genes to neuropsychiatric and neurodevelopmental disorders." (PMID 36803254, 2023). "This appears necessary because several genetic studies failed to classify CACNA1D missense variants as high-risk mutations and CACNA1D as a high-risk gene for neurodevelopmental disorders, including ASD." (PMID 31921405, 2020). "This nicely fits our prediction that only CACNA1D mutations which can also support channel gain-of-function confer high risk for neurodevelopmental disorders." (PMID 31921405, 2020). "We provide evidence that CACNA1D is a neurodevelopmental disorder-linked gene." (PMID 31921405, 2020). "Both CACNA1D and CACNA1G, which show high level of expression in the cerebellum, have been previously implicated in neurodevelopmental disorders." (PMID 41442065, 2025). "Based on these emerging discoveries, we suggest to include CACNA1D in genetic panels for diagnoses of neurodevelopmental disorders." (PMID 28472301, 2017). "Germline gain-of-function missense variants in the pore-forming Cav1.3 α1-subunit (CACNA1D gene) confer high risk for a severe neurodevelopmental disorder with or without endocrine symptoms." (PMID 36208199, 2023).
neurological disorders (9 papers, 2014 to 2025). "Several observations implicate CACNA1D alterations in the pathophysiology of psychiatric and neurological disorders." (PMID 28472301, 2017).
psychiatric disorder (8 papers, 2014 to 2025). A disorder characterized by behavioral and/or psychological abnormalities, often accompanied by physical symptoms. "The non-coding SNP rs893363, located in the 3′ UTR of CACNA1D and the putative promoter region of the choline dehydrogenase gene (CHDH), was found in a genome-wide analysis of five major psychiatric disorders including BD, SCZ, ADHD, MDD, and ASD." (PMID 31331039, 2019).
cardiac diseases (3 papers, 2018 to 2023). "These included the voltage gated calcium channel unit mentioned earlier, Cacna1d, as well as a key cardiac ubiquitin ligase, Nedd4l, which regulates sodium channel activity, with its mutations involved in various cardiac diseases including DCM." (PMID 37110207, 2023).
CACNA1D also shares sentences with these, for which no sentence is quoted: Anxiety (7 papers); diabetes (7); Sinus bradycardia (7); atrial fibrillation (6); Hearing impairment (6); heart failure (6); colon cancer (5); colorectal cancer (5); hyperaldosteronism (5); Arrhythmia (4); atrioventricular block (4); infection (4); Ataxia (3); brain disorder (3); cognitive deficits (3); hyperinsulinemic hypoglycemia (3); neurodegenerative disease (3); Parkinsonism (3); Primary hyperaldosteronism (3); familial hemiplegic migraine (2); Heart block (2); Hypoglycemia (2); melanoma (2); migraine (2); retinal degeneration (2); sick sinus syndrome (2); Usher syndrome (2); adrenal tumors (1); adrenocortical tumors (1); AIDS (1).
A further 68 diseases each share a sentence with CACNA1D in 1 paper.